RHOA (ras homolog family member A)
Diseases named in the same sentence as RHOA in open-access papers (continued):
Sharing a sentence is not in itself a finding about the gene and the disease.
tumor (continued). "This suggests a dual role of StarD13; as 1- a tumor suppressor which attenuates RhoA (hence Raf-1/MEK/ERK proliferation and survival pathway) as well as 2- an invasion suppressor, which inhibits Cdc42." (PMID 32900380, 2020). "The isoforms RhoA, RhoB and RhoC constitute the Rho-like group whose RhoA and RhoC promoting tumor growth while RhoB is a tumor suppressor." (PMID 31983155, 2020). "This clinical significance is likely attributed to altered RhoA activity disrupting the process of tumor invasion and metastasis when the process is impaired by RRAP mutation." (PMID 33288739, 2020). "Due to this, the potential role of RhoA and Rac1 in tumour development has attracted a great deal of attention from the research community in cancer biology." (PMID 32731493, 2020). "All this evidence supports the possibility that RhoA/SF-aligned periFN assembly suppresses in vivo tumor growth." (PMID 33158289, 2020). "Teng and Yi-Xue found that RhoA is a downstream target gene of miR-200b, and miR-200b can regulate the blood–tumor barrier permeability by directly targeting RhoA." (PMID 33336057, 2020). "Rho GTPase-activating protein 26 (ARHGAP26) is a negative regulator of the Rho family that converts the small GTP-binding protein RhoA (GTP-RhoA) to its inactive GDP-bound form and is a putative tumor suppressor gene associated with cell growth and migration." (PMID 31004081, 2019). "MSCs enhanced VEGF expression in tumor cells, accompanied with the activation of RhoA-GTPase and ERK1/2, and a “reprogramming” of tumor growth." (PMID 31130595, 2019). "Histopathological analysis revealed that small tumor nests were more frequent in RHOA mutants than in the mock or WT group." (PMID 31485674, 2019). "Apart from RHOA and TET2 mutations, a high frequency of diverse mutations in TCR signaling-related genes were also present in AITL tumor samples (11/12, 91.7%)." (PMID 30814910, 2019). "ROCK inhibition suppressed PDPN-induced tumor cell migration, highlighting the role of the RHOA/ROCK axis in CAF-dependent tumor invasion." (PMID 31106200, 2019). "Further studies confirmed that the inhibitory activity of Sema3F on GBM cell migration depends on NRP2 expression, suppressed by hypoxia in the tumor context, and on the subsequent RhoA inactivation." (PMID 31052281, 2019). "M3R has been suggested to activate mitogen-activated protein kinase (MAPK), Akt, or ras homolog family member A (RhoA), thereby contributing to tumor growth in various cancers." (PMID 31405140, 2019). "In conclusion, the modification of tumor microenvironment, such as cytoskeletal change and matrix remodeling via RhoA-YAP in CAFs, modulates OSCC invasion." (PMID 30921404, 2019). "We then used in vitro models to demonstrate that in CRC cells, miR-133a-3p directly targeted the regulation of RhoA that triggered tumor motility/invasion." (PMID 30678736, 2019). "S1PR1 is a G-protein-coupled receptor whose interaction with RhoA can regulate many functions of tumor cells, including cell growth, survival, migration, and morphogenesis." (PMID 30814488, 2019). "RHOA mRNA and its protein expression have demonstrated clinical relevance, including overall survival and GC tumor stage, and in this section, we searched for RHOA clinicopathological associations out of the 63 publications in the previous section." (PMID 31156701, 2019). "Smurf1 interacts with a tumor suppressor, RASSF1A (Ras association domain family member 1), to enhance the ubiquitination of RhoA; therefore, RhoA levels are decreased and tumorigenesis is suppressed." (PMID 31248165, 2019). "RhoA belongs to the Rho GTPase superfamily and is abnormally expressed in many malignant tumors and involved in the tumor invasion and metastasis, contributing to the occurrence and development of cancer." (PMID 31004081, 2019). "These latest discoveries, therefore, suggested a possible tumor suppressor function for RhoA in cancers." (PMID 31705019, 2019).
tumor (continued). "After VEGF-A binding, tip cells up-regulate cell proliferation, cytoskeleton remodeling and migration pathways (MAPK, PI3K/AKT, RhoA), sprout toward tumor cells and activate the adjacent ECs (stalk cells) to form new tumor vessels." (PMID 30834247, 2019). "Further mechanistic studies are needed to better elucidate the regulation of the RhoA signaling pathway in tumor metastasis, especially in HCC." (PMID 31339860, 2019). "We next examined the correlation of tumor level of Pin1, RhoA and RhoC transcripts with the clinicopathological parameters of the HCC patients." (PMID 31324164, 2019). "Beyond paracrine loops, the combination of in vitro and in vivo imaging has provided evidence that physical contacts between macrophages and tumor cells correlate with invadopodium formation through the induction of RhoA activity on tumor cells." (PMID 31214174, 2019). "In this study, we have identified an original role of Ran in the vicinity of the PM to control tumor cell invasion by functionally and specifically linking it to RhoA signaling." (PMID 31209254, 2019). "An interaction between claudin-11 and p190A is required to downregulate RhoA at intercellular junctions in order to maintain stable cell–cell contacts during dissemination of these circulating tumor cells." (PMID 31013840, 2019). "In summary, trafficking of LPAR1 mediated by N-WASP is crucial for the coupling of LPAR1 signaling with RhoA-mediated actomyosin contraction and force generation during tumor cell chemotaxis, invasion, and dissemination." (PMID 31668663, 2019). "First, proteins from red meat and dairy products were demonstrated to have a significant correlation with the overexpression of RhoA in favor of growing tumor cells to lymph nodes (ALNM) and VI+ patients." (PMID 31333806, 2019). "In fact, NT cells treated with IL-10 produced tumor activator factors such as RhoA, the glia maturation factor beta, galectin-1, the isocitrate dehydrogenase subunit alpha, and the D-3-phosphoglycerate dehydrogenase." (PMID 31766635, 2019). "Downregulation of RhoA by p190A at intercellular junctions is required to maintain stable cell–cell contact during dissemination of circulating tumor cells." (PMID 31013840, 2019). "Significantly, expression of RhoAT19N had the same effect on lung metastasis as the knockdown of RhoA expression in 4T1 cells and with a minimal effect on tumor weights." (PMID 31705019, 2019). "RHOB has therefore been suggested to have a tumor suppressor role, while RHOA and RHOC are considered oncogenes." (PMID 31888022, 2019). "RhoA/ROCK signalling has also been implicated in extracellular matrix (ECM) remodelling and tissue stiffness, which are associated with tumour aggressiveness." (PMID 29867097, 2018). "It is of note that GPCR signalling associated with ∆133TP53 mRNA expression in these tumours is upstream of the JAK-STAT and RhoA-ROCK pathways." (PMID 29343721, 2018). "RhoA and RhoC have been suggested in many studies to contribute positively to tumor development, but the role of RhoB in cancer remains elusive." (PMID 29385717, 2018). "After 17 days of treatment, the tumor volume for Ad-RhoA-RhoC was (444.38 ± 63.03) mm3 whereas for the control and Ad-HK groups it was (699.62 ± 190.56) mm3 and (678.81 ± 155.39) mm3, respectively." (PMID 29861465, 2018). "In contrast, Ras homolog family member A (RhoA) was less intensely stained in the invasion front compared to the central tumour area in 27/30 cases." (PMID 29976164, 2018). "Adenoviral-mediated combined delivery of RhoA and RhoC in colorectal carcinoma reduced 37% of tumor volume." (PMID 29861465, 2018). "On the other hand, the Ad-RhoA-RhoC-containing group exerted a relatively slow tumor growth (2.38-fold) and reduced approximately 37% of tumor volume in comparison to the control group." (PMID 29861465, 2018).
tumor (continued). "Mice treated with anti-RhoA siRNA (tumor volume, 200 mm3) and anti-RhoC siRNA (tumor volume, 600 mm3) showed less tumor growth than in the control group (1300 mm3)." (PMID 29861465, 2018). "We propose a model in which statins block the secondary EMT and outgrowth of tumor cells by preventing Ras, Rac, and RhoA prenylation." (PMID 30458856, 2018). "RhoA activation is known to be integral to the promotion of growth, migration, and dissemination of tumor cells, and elevated PTP4A3 expression levels are reported to alter RhoA activity." (PMID 29492190, 2018). "FilGAP and ArhGAP22 activation by RhoA/ROCK have been suggested to play a role in the RhoA/Rac1 antagonism of tumor cells, but inactivation of specific GEFs (p115RhoGEF, LARG, PDZ-RhoGEF) can also contribute to reduced Rac1 activation." (PMID 30048510, 2018). "First, statin treatment destabilizes the cytoskeletal structure of tumor cells in a RhoA/RhoC-dependent manner." (PMID 30458856, 2018). "As we previously reported, SEMA3F-NRP2 interactions result in the cytoskeletal collapse in tumor cells and ECs via the RhoA pathway." (PMID 30532711, 2018). "Recombinant adenovirus-based shRNA-targeted RhoA and RhoC (Ad-RhoA-RhoC) were synthesized and subjected to animal studies for evaluating anti-tumor efficacy." (PMID 29861465, 2018). "Subsequent studies by the Klagsbrun lab demonstrated that a small GTPase RhoA plays a key role in mediating SEMA3s-induced collapsing activity in tumor cells and ECs." (PMID 30532711, 2018). "Although we identified a correlation between RhoA activation and tumor volume doubling time in vivo, the Y27632 inhibition of ROCK did not affect primary tumor growth." (PMID 29535813, 2018). "Among these genes, we focused on CA9, because previous studies have shown that CA9 promotes tumor cell migration and invasion in vitro by inhibiting the RHOA pathway, and is highly expressed in younger patients with cervical and hepatocellular malignancies." (PMID 30034621, 2018). "The contact with CM derived from tumour‐activated BM‐MSCs induces a significant decrease of bound Rac1‐GTP with a parallel increase of bound RhoA‐GTP in OS cells." (PMID 29517849, 2018). "Tumor-derived capillary endothelial cells harbor a high level of active RhoA and ROCK to exhibit aberrant vessel formation through mechanosensing abnormalities at the interface between endothelial cells and the extracellular matrix." (PMID 29659486, 2018). "RNAi therapy targeted to RhoA and RhoC genes is supposed to be more effective to suppress tumor growth than conventional therapy." (PMID 29861465, 2018). "For example, MET is a proto-oncogene, KRAS is a proto-oncogene, and overexpression of RHOA leads to tumor formation." (PMID 29293623, 2018). "To assess the role of adherens junction proteins – in CAF-promoted scattering of tumor cells – we examined the expression of E-cadherin and phospho-p120 catenin, which regulates RhoA activity." (PMID 29535813, 2018). "The signalling pathways coordinated with RhoA and Rac1 activities play pivotal roles in tumor metastasis." (PMID 28841878, 2017). "DLC1 is primarily involved in regulating the Rho GTPases (RhoA and Cdc42), which are involved in cancer-related signalling and are closely related to the occurrence and development of tumours." (PMID 29212270, 2017). "The GS tumours, nearly diploid tumours, are correlated to diffuse histological variant and alterations of genes CDH1 and RHOA." (PMID 29094049, 2017). "Ovarian cancer cells express high levels of S100A4 mRNA and protein to increase tumor cell invasiveness and for the upregulation of RhoA activity." (PMID 29069865, 2017).
tumor (continued). "Overexpression of GGTase-Iβ or constitutively active RhoA abolished the enhancement by inhibiting HDAC1 on anti-tumor effects of statins." (PMID 28481295, 2017). "Migration, in part regulated by RhoA, Rac1 and cdc42 small G-proteins, has a pivotal role in tumor progression and metastasis formation." (PMID 28562340, 2017). "The members of the Ras superfamily of small GTPases, such as Rac1, Cdc42, and RhoA, are adhesion and growth factor-activated molecular switches that play important roles in tumor development and progression." (PMID 28811522, 2017). "Recently, the RhoA/ROCK1 signaling pathway has received considerable attention for its involvement in tumor formation and progression." (PMID 28184030, 2017). "One possibility is that the G17V RHOA mutation occurs in TET2-mutated premalignant cells and facilitates the selective differentiation of TET2-mutated premalignant cells into tumor cells with the TFH phenotype." (PMID 28157189, 2017). "In this study, we show that PAD2 depletion or inhibition suppresses tumor cell migration, alters tumor cell morphology, and suppresses the expression of the cytoskeletal regulatory proteins: RhoA, Rac1, and Cdc42." (PMID 28549415, 2017). "The motility and metastasis of tumor cells are controlled by RhoA and Rac1, and activation of ERK participates in stress fiber formation through inhibition of RhoA." (PMID 28841878, 2017). "The Rho family of GTPases is composed of RhoA, RhoB and RhoC and regulates the cytoskeleton, playing essential roles in cell polarity, division, proliferation, apoptosis and tumor cell metastasis." (PMID 28741985, 2017). "RHOA mutations were identified only in PD1+ cells in 100% cases, while TET2 and DNMT3A mutations were identified in both the PD1+ cells and CD20+, tumor-cell-depleted cells in the majority of cases." (PMID 28157189, 2017). "This means that the primary tumor has cells that use rhoA/ROCK signaling and undergo ameboid metastasis to lymphatics, as well as cells that use reactive oxygen/Akt signaling and undergo mesenchymal hematogenous metastasis to distant sites." (PMID 28825045, 2017). "All the RHOA and IDH2 mutations were confined to the PD1+ cells, indicating that some, including RHOA and IDH2 mutations, being specific events in tumor cells." (PMID 28157189, 2017). "DLC1 is a GAP primarily for RhoA and has been mainly studied in cancer research as a tumor suppressor." (PMID 28358928, 2017). "While RhoA and C promote invasion and metastasis formation through regulation of actin cytoskeleton dynamics, several findings suggest that RhoB has a tumor suppressor activity through its pro-apoptotic function." (PMID 28212429, 2017). "DT also suppressed the expression of tumor epithelial–mesenchymal transition genes, including RhoA and SNAI1." (PMID 28157698, 2017). "It was established that the RhoA/ROCK signaling pathway regulated abundant tumor cellular processes ranging from proliferation, growth and invasion to cytoskeletal remodeling and gene expression." (PMID 28184030, 2017). "In this pathway, miR-133b is an element in a feedback loop including TAp63 and RhoA, which greatly enhances the TAp63-related apoptosis signal and avoids abnormal proliferation in tumor cells." (PMID 27894087, 2016). "Prominent pathways that are activated downstream of integrin binding are the FAK, PI3K, ERK and RhoA pathways which drive a range of pathological functions including tumour cell migration and invasion." (PMID 27556857, 2016). "As predicted from the results of other previous studies and confirmed in the present study, the higher the RhoA activity the more efficient the DNA repair; this phenomenon is common to many human tumor cells." (PMID 26823948, 2016). "Overall, of the two GC xenograft models, RHOA knockdown suppressed tumor growth in both, reaffirming its role in GC oncogenesis." (PMID 27806312, 2016).
tumor (continued). "In tumor cells invading a rigid extracellular matrix environment, an upregulation of Rac1 activity and a concomitant downregulation of RhoA has been noted, similar to the signaling which has been observed during neural crest migration." (PMID 27589803, 2016). "In a model of colorectal cancer, RhoA was found to function as a tumor suppressor, with its inactivation being required for canonical signaling downstream of Wnt3a to promote metastasis." (PMID 27589803, 2016). "We determined the expression of RhoA/B/C in tumor cells before and after co-culturing with BMMCs by Western blotting." (PMID 26978404, 2016). "In cancer cells, reducing β4 expression increases RhoA activity, potentiates cell migration and invasiveness, primary tumour growth and metastatic spreading, by promoting the acquisition of an amoeboid–mesenchymal hybrid phenotype." (PMID 27917859, 2016). "For instance, the E3 ligase SMURF1 targets RhoA for degradation at the leading edge of migrating cells, affecting tumor cell migration." (PMID 27104658, 2016). "RhoA overexpression has been reported in breast, colon, lung, and gastric tumors, and it facilitates cancer progression by inducing increased tumor cell motility, proliferation, and survival, as well as a loss of cell polarity." (PMID 26649141, 2016). "A recent findings showed that podoplanin assisted lung tumor cells with local invasion; that is tumor cells invaded by following the podoplanin-positive CAFs into surrounding extracellular matrix through RhoA activation." (PMID 27996035, 2016). "Although the RhoA/ RhoA kinase (ROCK) signaling pathway is implicated in DPT-stimulated cytoskeleton remodeling and tumor vasculature suppressing, the detailed mechanisms by which DPT mediates these effects are poorly understood." (PMID 26470595, 2015). "Despite the fact that overexpression of RhoA was reported in many cancer types, the actual role of RhoA in tumor progression depends on context." (PMID 26470595, 2015). "Numerous cellular studies have indicated that RhoA signaling is required for oncogenic Ras-induced transformation, suggesting that RhoA is a useful target in Ras induced neoplasia." (PMID 26030593, 2015). "It is well established that Ras homologous (Rho) GTPases family proteins, like Rac1 and RhoA, play a key role in cell migration and tumor metastasis by regulating actin dynamics and cell-cell adhesion." (PMID 26156017, 2015). "The Cip/Kip proteins have been reported to modulate the RhoA/ROCK/LIMK/cofilin signaling pathways involved in tumor invasion and metastasis." (PMID 26271467, 2015). "In most cases, RhoA activation carries out the tumor vasculature suppressing effect of microtubule destabilizer when it is a downstream effector of microtubule depolymerization, consistent with our findings." (PMID 26470595, 2015). "Rho GTPases, members of the Ras superfamily of small GTPases such as Rac1, Cdc42, and RhoA, are adhesion and growth factor–activated molecular switches that play important roles in tumor development and progression." (PMID 26371759, 2015). "Tang and colleagues reported that the over-expression of eukaryotic initiation factor 5A2 enhanced cell motility and promoted tumor metastasis by activating RhoA/Rac1 to stimulate the formation of stress fibers and lamellipodia in HCC." (PMID 26498692, 2015). "Apart from its regulatory role in PI3K pathway, the miR-126 was recently found to exert a role of tumor suppressor by inhibiting RhoA/ROCK signaling pathway through a mechanism of repressing RhoA expression." (PMID 26064956, 2015). "In summary, the current study reveals that PIWIL2 interacts with NME2 and facilitates NME2 binding to G4-motif to promote c-Myc expression, contributing to tumor cell proliferation and filamentary F-actin modulation via regulating RhoA expression." (PMID 25193865, 2014). "ErbB-2-overexpressing tumours depend on Plexin-B1-mediated RhoA activation for tumour progression and metastasis." (PMID 25137062, 2014).